CCL18 (C-C motif chemokine ligand 18)
Diseases named in the same sentence as CCL18 in open-access papers (continued):
Sharing a sentence is not in itself a finding about the gene and the disease.
autoimmune disease (1 paper, 2013). A disorder resulting from loss of function or tissue destruction of an organ or multiple organs, arising from humoral or cellular immune responses of the individual to their own tissue constituents. "It was reported that CCL18 was correlated to the autoimmune disease." (PMID 23697837, 2013).
Autoimmunity (1 paper, 2017). The occurrence of an immune reaction against the organism's own cells or tissues. "The safety and lack of autoimmunity secondary to CD4-AsiC knockdown of PITPNM3 or antibody inhibition of CCL18, PITPNM3 or CCR8 will need to be examined carefully to evaluate potential therapeutic applications." (PMID 28290464, 2017).
B-cell lymphoma (1 paper, 2024). "CCL18 is known to increase the proliferation of B-cell lymphoma and may contribute to immune evasion from its effect on immune surveillance mediated by macrophages and dendritic cells and by simultaneously favoring T cell-tolerance." (PMID 40809150, 2024).
Becker muscular dystrophy (1 paper, 2021). Becker muscular dystrophy (BMD) is a neuromuscular disease characterized by progressive muscle wasting and weakness due to degeneration of skeletal, smooth and cardiac muscle. "In this study, we used a highly specific and reproducible MSD ELISA assay to examine the levels of the three chemokines (CXCL10, CCL2, and CCL18) in serum and muscle samples collected from DMD patients, Becker muscular dystrophy (BMD) patients, and age-matched healthy controls." (PMID 34440571, 2021).
brucellosis (1 paper, 2024). Brucellosis is a bacterial infection that spreads from animals to people via unpasteurized dairy products or by exposure to contaminated animal products or infected animals. "We found that NK cells, especially for NK_Naive, NK_Memory and NK_CD56(dim), in brucellosis patients potentially underwent migration, with several migration‐related genes highly expressed like CCL4, CXCR5, CCL18, CXCL2, and so forth." (PMID 39135683, 2024).
chitotriosidase deficiency (1 paper, 2023). The chitotriosidase gene is assigned to chromosome 1q31-q32. "The chemokine, CCL18, is an alternative option for disease monitoring in patients with chitotriosidase deficiency and was demonstrated to be released by Gaucher cells, highlighting its potential as a biomarker to monitor GD progression." (PMID 36782327, 2023).
diabetes type 1 (1 paper, 2017). "Effluent CCL18 levels were elevated in all samples analyzed from patients with diabetes type 1 (DM1) compared with patients without DM1, without association with serum CCL18 levels (data not shown)." (PMID 28414753, 2017).
diabetic nephropathy (1 paper, 2024). "However, the expression levels of CCL18 in the kidneys of diabetic nephropathy patients and in the abdominal subcutaneous fat and visceral fat of obese patients were not significantly different from those in the control groups." (PMID 39526504, 2024).
eczema (1 paper, 2019). "Eczema was associated with decreased concentrations of IFNα, IFNγ, TSLP, CXCL9, and CXCL13, but increased concentrations of CCL18 and Galectin-3." (PMID 31998285, 2019). "In addition, eczema was associated with decreased concentrations of IFNα, IFNγ, TSLP, CXCL9, and CXCL13, but with increased concentrations of CCL18 and Galectin-3." (PMID 31998285, 2019). "Although, within the INCA study, no increased risk was shown for doctor's diagnosed eczema after neonatal antibiotic treatment at 1 year of age, increased concentrations of Gal-3, CCL17 (TARC), and CCL18 (PARC) were detected within the infants with DDE." (PMID 31998285, 2019). "Moreover, we found that children with doctor's diagnosed eczema had limited capacity to induce Th1 cytokines (like IFN-gamma and CXCL9) and more eczema/skin related marker CCL18 (PARC)." (PMID 31998285, 2019).
emphysema (1 paper, 2021). "On the other hand, CCL18 was also reported as a major inducer of pulmonary cystic fibrosis and emphysema." (PMID 33802081, 2021). "The resulting sequelae, such as emphysema and fibrosis, can result in chronic hypoxia that maintains the expression of HIF-1α, decreasing CCL18 and up-regulating IL-12p40." (PMID 33802081, 2021).
eosinophilic disorders (1 paper, 2018). "In consonance with these actions, circulating CCL18 levels have been demonstrated to be a biomarker for disease activity and outcome in various fibrotic diseases, as well as in some eosinophilic disorders." (PMID 29850544, 2018).
head and neck cancer (1 paper, 2019). A primary or metastatic malignant neoplasm affecting the head and neck. "CCL18 has been identified to function importantly in the invasion and metastasis of human cancers including head and neck cancer 13-16." (PMID 31839826, 2019).
hepatitis C (1 paper, 2021). "A protective role of CCL18 was shown in experimental malaria, and was associated with the maintenance of chronic inflammation in the lungs and liver, during tuberculosis and hepatitis C, respectively." (PMID 33802081, 2021).
HIV-1 infection (1 paper, 2019). The type species of lentivirus and the etiologic agent of acquired immunodeficiency syndrome (AIDS). "Taken together, these data suggest that although all three TH2 chemokines are increased during HIV-1 infection, only CCL18 and/or CCL18-producing cells play a role in CD4+ T cell recovery as experienced by some HIV-1-infected patients undergoing cART." (PMID 30979916, 2019). "Here, we report that plasma levels of CCL18 are significantly increased during HIV-1 infection and negatively correlate with CD3+CD4+ T cell counts in patients on combination antiretroviral therapy (cART) with a suppressed viral load." (PMID 30979916, 2019). "Presented data shows that the chemokines, CCL17, CCL18, and CCL22 are increased during HIV-1 infection." (PMID 30979916, 2019).
infectious peritonitis (1 paper, 2018). Inflammation of the peritoneum due to infection by bacteria or fungi. "We found that the peritoneal concentration of CCL18 was increased approximately 5-fold in effluents from patients with infectious peritonitis compared with reported values in uninfected samples." (PMID 29850544, 2018). "We evaluated CCL18 concentrations in serial samples from four of the PD patients with infectious peritonitis (IP)." (PMID 29850544, 2018).
inflammatory breast carcinoma (1 paper, 2019). An advanced, invasive breast adenocarcinoma characterized by the presence of distinct changes in the overlying skin. "In inflammatory breast cancer (IBC), tumor cells interact with immune suppressing M2-TAM leading to the production of high levels of IL-8 and CCL18 chemokines that in turn activate STAT3, which induces a CSCs-like phenotype in IBC cells and drives EMT during IBC progression." (PMID 31709180, 2019).
inflammatory skin disease (1 paper, 2021). Inflammatory skin disorders covers a broad category that includes many conditions ranging in severity, from mild itching to grave medical health complications These disorders are common in people of all ages and races. "CCL17 and CCL18 are chemokines that are significantly involved in T cell–mediated reactions and characteristic for various inflammatory skin diseases with TH2 dominance." (PMID 34925353, 2021).
interstitial cystitis (1 paper, 2025). A rare chronic debilitating urogenital disease characterized by urinary frequency, urgency, and pelvic pain. "There is no existing literature that clarifies the relationship between CCL18, MMP10, and WIF1 with interstitial cystitis." (PMID 40435311, 2025).
kidney cancer (1 paper, 2010). Primary or metastatic malignant neoplasm involving the kidney. "The best three single gene discriminators are found to be UMOD, ACPP and CCL18 for kidney cancer, having the same classification accuracy, 98.6% on the training set and 100% and 94.4%, 95.7% and 86.11% and 89.4% and 68.1% on the two test sets, respectively." (PMID 21060876, 2010).
leishmaniasis (1 paper, 2024). Infectious disease that is transmitted through the bite of hematophagous female phlebotomine sand flies. "In leishmaniasis, the CCL18 is related to the polarization of M2 macrophages, negative regulation of pro-inflammatory cytokines, and recruitment of Th2 cells." (PMID 38743668, 2024).
leprosy (1 paper, 2014). Leprosy is a chronic infectious disease affecting primarily the skin and peripheral nervous system. "In order to adjust for age we analyzed CCL17 and CCL18 associations with leprosy phenotype in patients born before 1966 (cutoff age of 45)." (PMID 25412496, 2014). "CCL17 and CCL18, were more strongly associated with leprosy polarity than traditional TH1 and TH2 cytokines." (PMID 25412496, 2014). "Our findings suggest that CCL17 and CCL18 dermal expression is associated with leprosy polarity." (PMID 25412496, 2014). "Furthermore, evidence that CCL18 may play a direct role in leprosy is suggested by linkage and genome wide association studies that show several CCL18 polymorphisms are associated with development of leprosy." (PMID 25412496, 2014). "The primary finding of our study is that dermal mRNA levels of CCL17 and CCL18, two chemokines important in the development of a TH2 T-cell response, are associated with tuberculoid and lepromatous leprosy respectively." (PMID 25412496, 2014). "Herein we show that two chemokines, CCL17 and CCL18, more accurately define leprosy polarity than traditional TH1 and TH2 cytokines." (PMID 25412496, 2014). "Interestingly, our study demonstrated that CCL17 and CCL18 distinguished leprosy polarity with greater accuracy than the traditional TH1 and TH2 cytokines (IL10, IFNG)." (PMID 25412496, 2014). "Our study may be underpowered to determine a significant association between CCL18 and CCL17 serum levels and leprosy phenotype." (PMID 25412496, 2014). "Mycobacterial antigens present in leprosy lesions could also stimulate the direct production of CCL18, since this has been described in monocyte derived macrophages and primary alveolar macrophages." (PMID 25412496, 2014). "In the GWAS study, three of eight CCL18 polymorphisms were significantly associated with susceptibility to leprosy using a conventional significance threshold (but not GWAS level significance)." (PMID 25412496, 2014). "We found that three soluble mediators (CCL17, CCL18 and IL10) and one cell marker (CD14) were differentially expressed in leprosy dermal lesions." (PMID 25412496, 2014). "Next the serum levels of CCL17 and CCL18 were compared in 6 EC (5 from Nepal and one from non-endemic area) patients without leprosy, versus 20 patients with leprosy (11 with BT, 2 with BL, and 7 with LL by RJ classification as determined by biopsy)." (PMID 25412496, 2014).
Löfgren's syndrome (1 paper, 2010). "Neither did we observe any difference in CCL18 expression between patients with Löfgren's syndrome or not." (PMID 20813038, 2010).
MALT lymphoma (1 paper, 2021). An indolent, extranodal type of non-Hodgkin lymphoma composed of small B-lymphocytes (centrocyte-like cells). "In addition, several molecules such as CXCL13, CCL18, CCL19, CCL 20 and TLR 10 were found to be dysregulated in MALT lymphoma, suggesting that not only modulate H. pylori infection but also affect the risk of MALT lymphoma." (PMID 35008340, 2021).
mediastinal lymphoma (1 paper, 2007). "Recent findings suggest that expression of chemoattractants, such as CCL18, CCR6, and CCL20, on neoplastic epithelium in MNT can promote the recruitment of MALT, the emergence of monoclonal B cells, and, eventually, the subsequent development of mediastinal lymphoma." (PMID 17498299, 2007).
migraine (1 paper, 2021). "We can speculate that increased release of CCL18 observed in patients with migraine in combination with other pro-inflammatory mediators is likely to contribute to a persistent inflammatory state that may trigger the onset of MD in susceptible individuals." (PMID 34575163, 2021). "We could observe that the levels of CCL18 were higher in patients with MD or migraine when they were compared to controls." (PMID 34575163, 2021). "The levels of CCL18, CCL22, and CCL4 were different between patients with MD or migraine and controls." (PMID 34575163, 2021). "The levels of CCL18, CCL3, and CXCL4 were different between patients with MD or migraine and controls." (PMID 34575163, 2021). "However, CCL18 levels did not allow to distinguish between MD and migraine (p = 0.74)." (PMID 34575163, 2021). "Therefore, we measured the levels of IL-1β, CCL3, CCL4, CXCL1, CCL22, and CCL18 in a cohort of 83 patients with MD, which included 44 EOMD and 39 LOMD, and 64 patients with migraine without vestibular symptoms to control the effect of migraine itself on cytokine levels." (PMID 34575163, 2021).
monoclonal gammopathies (1 paper, 2007). "Plasma CCL18 levels have been reported to be elevated in Gaucher patients, but no definitive relationship with monoclonal gammopathies could be identified." (PMID 17655728, 2007).
multiple sclerosis (1 paper, 2020). A progressive autoimmune disorder affecting the central nervous system resulting in demyelination. "Association of PC and CCL18 concentrations with MRI characteristics in multiple sclerosis patients." (PMID 33178104, 2020).
onchocerciasis (1 paper, 2022). Onchocerciasis is a form of filariasis, caused by the parasitic worm Onchocerca volvulus, transmitted by the black fly. "In onchocerciasis patients at baseline, the OvAg-induced cytokine IL-10 production correlated positively with IFN-γ (R = 0.371, P = 0.0022), with CCL17 (R = 0.471, P < 0.0001) and with CCL18 (R = 0.322, P = 0.008)." (PMID 35503786, 2022).
Oral leukoplakia (1 paper, 2021). A thickened white patch on the oral mucosa that cannot be rubbed off. "In fact, in a study focused on the alterations of chemokine and chemokine receptors in premalignant stages of OSCC, CCL18 was the top one gene significantly upregulated in oral leukoplakia samples in comparison with normal epithelia." (PMID 34025655, 2021).
Osteopenia (1 paper, 2024). Osteopenia is a term to define bone density that is not normal but also not as low as osteoporosis. "We previously reported that plasma TRAP5b levels are increased in patients with GD, associated with osteopenia and osteoporosis, and positively correlated with GD clinical biomarkers CCL18, Lyso-Gb-1, and Chito." (PMID 38667330, 2024).
osteoporosis (1 paper, 2024). A condition of reduced bone mass, with decreased cortical thickness and a decrease in the number and size of the trabeculae of cancellous bone (but normal chemical composition), resulting in increased fracture incidence. "The positive correlations between TRAP5b and GD-specific biomarkers, Lyso-Gb-1, CCL18, and Chito, with the lower BMD Z-score suggest that the accumulation of glucosylsphingosine may play a crucial role in the development of osteoporosis in patients with GD." (PMID 38667330, 2024).
ovarian tumor (1 paper, 2023). "The ligands CCL1 and CCL18 corresponding to CCR8 were significantly overexpressed in ovarian tumor tissues, and the CCR8-CCL1 and CCR8-CCL18 axis played a key role in the migration and infiltration of CD4+CCR8+ Tregs into ovarian tumor tissues." (PMID 37950246, 2023).
plaque psoriasis (1 paper, 2021). "C-C motif chemokine ligand 18, chitinase-3-like protein 1 and azurocidin were significantly elevated in the plasma from plaque psoriasis patients with high anti-CA levels and severe disease." (PMID 33546306, 2021). "Increased CCL18, CHI3L1 and AZU1 levels were detected in plasmas from plaque psoriasis, but we could not confirm their association with anti-CA IgA levels, which remains a limitation of the study." (PMID 33546306, 2021).
prostate tumor (1 paper, 2014). "The efficiency of CCL18 on prostate tumor growth was assessed in a subcutaneous xenograft model." (PMID 25197632, 2014).
pulmonary TB (1 paper, 2021). "When only the individuals with pulmonary TB were compared to those with ORD, significant differences were observed for SAA, CRP, VEGFR3, RANTES, Pentraxin3, Ferritin, CCL18, MPO, GDF-15, MMP-1, PDGF-BB, Procalcitonin, MDC, Myoglobin, and VCAM-1." (PMID 33732236, 2021).
radiation pneumonitis (1 paper, 2017). Inflammation of the lung due to harmful effects of ionizing or non-ionizing radiation. "The present study was designed to evaluate CCL18 as a predictor for early RILT i.e. radiation pneumonitis as defined per NCI Common Terminology Criteria for Adverse Events v4.03." (PMID 28957436, 2017). "In this study we aimed to analyze the role of CCL18 as a prognostic biomarker for the development of early radiation induced lung toxicity (RILT), i.e. radiation pneumonitis after thoracic irradiation and its significance in the course of the disease." (PMID 28957436, 2017).
salivary gland tumors (1 paper, 2025). "In patients with salivary gland tumors (WT and PA), various chemokines have been determined, including CCL28, CXCL10, CXCL12, CCL18, and CXCL1, as well as pro-inflammatory cytokines such as IL-1β, IL-6, IL-4, IL-17, and IL-33." (PMID 40807046, 2025).
Splenomegaly (1 paper, 2025). Abnormal increased size of the spleen. "Lyso-Gb1 levels correlated with CHITO (r = 0.59 p < 0.001), CCL18 (r = 0.62 p < 0.001), hepatomegaly (r = 0.28 p < 0.001), splenomegaly (r = 0.27 p = 0.003), treatment mode (p < 0.001) and, interestingly, splenectomy (p = 0.01)." (PMID 40710527, 2025).
Stroke (1 paper, 2024). Sudden impairment of blood flow to a part of the brain due to occlusion or rupture of an artery to the brain. "In the univariate analysis for the total patient population at one year, CCL18 was strongly associated with all-cause mortality (p < 0.001), cardiac death (p = 0.005), MI (p = 0.012) and with stroke (p = 0.015)." (PMID 38596196, 2024). "In the univariate analysis for the total patient population at two years, the association of CCL18 with all-cause mortality was weaker (p = 0.087) but remained significant for cardiac death (p = 0.013), MI (p = 0.002) and stroke (p = 0.003)." (PMID 38596196, 2024). "In patients with non-AMI, however, univariate analysis showed a positive association between CCL18 and all-cause mortality (p < 0.001), cardiac death (p = 0.024), MI (p = 0.009), and stroke (p = 0.019)." (PMID 38596196, 2024). "However, our findings do not support an independent association between CCL18 and future cardiovascular events, such as MI, stroke and cardiac mortality, and the independent association with total mortality was restricted to the non-AMI patients." (PMID 38596196, 2024). "Furthermore, no independent association was found between CCL18 and MI or stroke during the entire follow-up period." (PMID 38596196, 2024).
tuberculoid leprosy (1 paper, 2014). A principal or polar form of leprosy in which the skin lesions are few and are sharply demarcated. "Of the 24 soluble mediators of inflammation that were measured, 7 showed significant differences between lepromatous and tuberculoid leprosy (CCL2, CCL17, CCL18, IFNA1, IL10, IL22, and TNF)." (PMID 25412496, 2014).
type 2 diabetic nephropathy (1 paper, 2024). "CCL18 expression levels in the kidneys of type 2 diabetic nephropathy patients and in the abdominal subcutaneous fat and visceral fat of obese patients were not significantly different from those in the control groups (p > 0.05)." (PMID 39526504, 2024).
ulcerative colitis (1 paper, 2025). An inflammatory bowel disease involving the mucosal surface of the large intestine and rectum. "The identified immune biomarkers (CCL18, DUOX2, GREM1, LCN2, and TNC) demonstrated strong diagnostic efficacy and are key immune genes for ulcerative colitis (UC)." (PMID 40584713, 2025). "The expression levels of core immune genes including CCL18, DUOX2, GREM1, LCN2, and TNC in ulcerative colitis models were detected by fluorescence q-PCR." (PMID 40584713, 2025).